BDNF (brain derived neurotrophic factor)
Diseases named in the same sentence as BDNF in open-access papers (continued):
Sharing a sentence is not in itself a finding about the gene and the disease.
Stroke (continued). "Intranasal administration of CART 3 days after MCAO increased brain CART levels, up-regulated BDNF expression, enhanced NSCs survival, proliferation and migration, improved neurological function, and promoted nerve regeneration in stroke animals." (PMID 39228411, 2024). "National Institutes of Health Stroke Scale (NIHSS) scores were negatively correlated with BDNF levels in a previous study on AIS patients, but positively correlated with miR-124." (PMID 39001884, 2024). "Herein, we used data from the largest genome-wide association study (GWAS) to date on plasma BDNF levels, along with a statistical summary of seven common neurological disorders (AD, PD, ALS, MS, epilepsy, stroke, and migraine)." (PMID 38707431, 2024). "The BDNF has been shown to mediate oligodendrogenesis and remyelination and play a key role in angiogenesis, synaptogenesis and functional recovery after stroke." (PMID 38520223, 2024). "Some authors compared aerobic exercise with HIIT in patients with stroke and found larger increments in BDNF levels and longer maintenance of those BDNF and irisin levels." (PMID 38610750, 2024). "Studies on developing rehabilitation strategies aimed at facilitating and maximizing functional outcomes post-stroke showed an emergent role of BDNF as a key facilitator of neuroplasticity involved in motor learning and rehabilitation after stroke." (PMID 39519537, 2024). "Given the complexity of stroke pathology and the multifaceted roles of lipids and BDNF in the brain, further research in this area is necessary." (PMID 38397057, 2024). "In an experimental stroke model, the administration of BDNF through the nasal route was found to increase anti-inflammatory cytokine IL-10 levels but to decrease pro-inflammatory cytokine tumour necrosis factor-alpha levels." (PMID 38707431, 2024). "Several papers in preclinical stroke studies have found that BDNF plays an integral role in the relationship between rehabilitation and recovery." (PMID 38397427, 2024). "Intracellular investigations can be conducted to investigate the impact of exosomes on stroke when combined with BDNF." (PMID 39095888, 2024). "BDNF (Brain-derived neurotrophic factor): This protein plays a role in the survival and growth of brain cells and has been found to be reduced in people who have had a stroke." (PMID 40777969, 2024). "Specifically, to assess the effects of HF-rTMS on post-stroke neurogenesis, we measured plasmatic levels of miRs106b~25 cluster and BDNF." (PMID 38540283, 2024). "CREB transcription factors are required for the early induction of all the major BDNF transcripts, and the activation of CREB-induced BDNF secretion is crucial for cortical circuit plasticity and functional recovery after stroke in mice." (PMID 38509618, 2024). "HIIT is more effective than MICT in improving aerobic capacity, cerebral oxygen utilization, serum BDNF levels, and neuronal activities in stroke patients." (PMID 39697960, 2024). "The BDNF val66Met single nucleotide polymorphism (SNP) leads to intracellular packaging of proBNDF and secretion of mature BDNF and is considered a key predictor of cognitive outcome and functional recovery after stroke in hospitalized patients." (PMID 38845616, 2024). "BDNF’s involvement in synaptic plasticity is especially relevant in stroke recovery, where synaptic reorganization is critical for motor and cognitive function restoration." (PMID 39519132, 2024). "Although BDNF is not currently used directly in clinical trials for nervous system tissue repair, other pharmacological drugs such as memantine, donepezil, and atorvastatin, are being investigated to enhance BDNF levels for stroke treatment." (PMID 39639374, 2024). "The BDNF level in stroke patients significantly decreased compared to the healthy control group, and its level decreased with the severity of the stroke." (PMID 39075604, 2024).
Stroke (continued). "After stroke, mice in an enriched environment have higher BDNF concentrations and improved cognitive performance compared to mice housed in a standard environment." (PMID 38397427, 2024). "Most studies in adult stroke models found a greater BDNF concentration, BDNF mRNA, and uptake of BDNF by astrocytes acutely from 2 h to 7 days post injury compared to sham-operated rats." (PMID 38397427, 2024). "While the individual roles of these serum lipids and BDNF in stroke pathology are well acknowledged, the precise nature of their interaction, especially in the context of IS, has not yet been fully elucidated." (PMID 38397057, 2024). "In initial clinical studies of adults post stroke, individuals who performed physical exercises had increased BDNF concentrations compared to pre-intervention and, in one study, BDNF serum concentrations were associated with cognitive recovery." (PMID 38397427, 2024). "Exosomes delivering Zeb2/Axin2 have been shown to enhance post-stroke neuroplasticity, increase neurogenesis, and boost the concentration of BDNF." (PMID 39095888, 2024). "Inversely, overexpression of BDNF in hippocampus of rats can effectively alleviate the depression-like behaviors after stroke." (PMID 38421829, 2024). "According to a systematic review and meta-analysis of ischaemic and haemorrhagic stroke, patients with stroke have reduced levels of circulating BDNF compared to those in controls." (PMID 38707431, 2024). "It has been observed that plasma levels of BDNF decrease in stroke patients, as it happens in other pathologies like atherosclerosis, diabetes mellitus and metabolic syndrome." (PMID 38610750, 2024). "Similar research had shown that low-frequency (1 Hz) rTMS improved cognitive function in patients with stroke, and regulated synaptic plasticity through BDNF signaling pathway." (PMID 38570868, 2024). "After stroke onset, BDNF can enhance local anti-inflammatory action by upregulating IL-10 and downregulating TNF-α expression." (PMID 37123377, 2023). "Brain-derived neurotrophic factor (BDNF) increases its secretion levels after stroke onset and protects the nerves by reducing the excitotoxic effects of glutamate." (PMID 37091130, 2023). "Post-stroke complications including cognition, fatigue, mental health, and appetite, along with serum levels of brain-derived neurotrophic factor (BDNF), and mid-upper arm circumference (MUAC) were assessed in groups pre-and post-intervention." (PMID 38260068, 2023). "An enriched environment increases fibronectin type III domain-containing protein 5 (FDNC5) and BDNF expression in the ipsilateral cerebral cortex of mice after stroke." (PMID 37484824, 2023). "Previous studies have repeatedly proven that low serum BDNF levels are significantly correlated to poor functional outcomes and high mortality, and that elevated BDNF levels after stroke are correlated to improvement of functional recovery." (PMID 37731856, 2023). "Brain-Derived Neurotrophic Factor (BDNF) is a nerve growth factor associated with elevated transcranial Doppler (TCD) velocities and increased risk of stroke in SCD patients." (PMID 36774398, 2023). "Our findings in acute and chronic models of experimental stroke revealed that 1,5-AF causes beneficial effects via the AMPK/PGC-1α/BDNF pathway." (PMID 37950725, 2023). "After a stroke event, reactive astrocytes upregulate the expression of BDNF and other neurotrophic factors, and the resulting levels have been demonstrated to be associated with the clinical and functional outcome." (PMID 37719764, 2023). "It is thus clear that regulation of BDNF expression has an irreplaceable role in promoting post-stroke neurogenesis." (PMID 37534033, 2023). "Together, these studies suggest that BDNF exerts favorable effects in post-stroke recovery due to its attenuation of cell death and promotion of neurogenesis." (PMID 37719764, 2023).
Stroke (continued). "In recent years, there are many studies on the relationship between BDNF and stroke, but little attention has been paid to proBDNF and MMP-9." (PMID 37735708, 2023). "Restoring BDNF levels in post-stroke patients has been proposed as a reliable method to reduce the risk of the development of PSD in them." (PMID 37895349, 2023). "By limiting the ability to achieve and sustain fast walking after stroke, gait deficits indirectly reduce the overall energetic stimulus elicited by walking training and, in turn, reduce BDNF release into circulation." (PMID 38196979, 2023). "They secrete neurotrophins such as brain-derived neurotrophic factor (BDNF), which are involved in ensuring synaptic plasticity and neuronal survival and have been linked to recovery after stroke in animal models." (PMID 37446295, 2023). "A study showed that C8-ceramide promoted BDNF secretion in microglia via protein kinase Cδ (PKCδ) and/or ε signaling pathway thereby accelerating post-stroke repairing." (PMID 37333888, 2023). "Animals in DREADD group exhibit significantly higher BDNF expression than control and sham group, suggesting brain plasticity is contributing to post-stroke recovery." (PMID 35809218, 2023). "Prior studies have successfully assessed the beneficial effects of a single bout of endurance on the BDNF in older adults, Parkinson’s disease, and the chronic post-stroke phase." (PMID 36671818, 2023). "A review that included 35 studies showed that BDNF levels were lower in patients with chronic heart failure and stroke, but higher in patients with unstable angina and myocardial infarction." (PMID 38145212, 2023). "Exercise-induced increased expression of BDNF and double cortin positive cells were observed in the ischemic hippocampus after stroke in rats." (PMID 36960421, 2023). "Although some studies have shown an association between certain cardiovascular diseases other than stroke and altered BDNF levels, the current evidence that BDNF is an important marker of disease should be strengthened." (PMID 38137853, 2023). "The interaction between FE particles coated with RGD-PLT facilitates the sustained release of FE at the stroke site, delivering the neurotrophic factors BDNF, GDNF, and bFGF to the brain." (PMID 37445979, 2023). "The group receiving HA hydrogels combined with BDNF resulted in a significantly higher number of new neurons in contrast to the control group following 9 weeks of stroke." (PMID 38680508, 2023). "This highlights the potential role of BDNF, measured within the acute stage of stroke (after 3 weeks), as an indicator of stroke results." (PMID 37873057, 2023). "Genetic polymorphisms were also found to affect the levels of brain-derived neurotrophic factor (BDNF), dopamine, and apolipoprotein E (APOE), which in their turn affect neuroplasticity, functional recovery, and the type of stroke." (PMID 37041905, 2023). "A significantly higher prevalence of cognitive dysfunction has been reported among patients with stroke with low serum BDNF levels than among healthy controls." (PMID 37373767, 2023). "The inverse relationship that miR-34a has with BDNF contributes to the finding that miR-34a increases post-stroke are deleterious to the healing process." (PMID 37927446, 2023). "Five studies comprising a total of 1111 patients (men: 693, women: 418) investigated the possible altered BDNF serum levels in stroke patients." (PMID 37895349, 2023). "The increased survival rate of genetically modified MSCs, generated via the co-overexpression of BCL2 + BDNF and BCLXL + BDNF, increases the likelihood of transplant survival after a stroke procedure, such as transplantation." (PMID 37371846, 2023). "The average increase in serum BDNF observed in this study was similar to the average post-acute exercise change reported in the post-stroke literature (2.49, 95% CI 1.10, 3.88)." (PMID 38196979, 2023).
Stroke (continued). "The relevance of BDNF scavenging by TrkB shedding in the context of stroke has been previously reported, worsening stroke-induced damage to neuronal cells." (PMID 36982466, 2023). "A key issue in studies of BDNF level measurement after stroke appears to be the time at which BDNF levels were measured." (PMID 38137853, 2023). "Experimental studies demonstrated clinically positive outcomes reached by administration of stroke treatments that modulate BDNF expression, leading to consider BDNF as potential therapeutic target." (PMID 37719764, 2023). "Clinically positive results have been demonstrated with several stroke treatments that manipulate BDNF levels, including administration of hormones and compounds targeting neurotransmitters, stem cell transplantation, and regulation of other related genes." (PMID 36969561, 2023). "In contrast, in another study, HA hydrogels containing brain‐derived neurotrophic factor (BDNF) were injected into the cranial cavities of mice within a week of stroke." (PMID 38680508, 2023). "The sub-group analysis for stroke period and treatment modality revealed that serum BDNF is closely correlated with the factors of subacute stroke and NIBS treatment, but not acute stroke and non-NIBS treatment." (PMID 37731856, 2023). "The quantitative analysis results revealed a moderate quality evidence that stroke rehabilitation significantly increased the level of brain-derived neurotrophic factor (BDNF) in serum." (PMID 37731856, 2023). "Our understanding of the duration of such positive effects, and especially of how long increased BDNF is maintained in stroke patients, should be deepened." (PMID 38137853, 2023). "BDNF protects neurons from apoptosis, a key process that directly leads to neuronal cell death and brain damage after stroke, by activating downstream PI3K/Akt and MAPK/ERK pathways." (PMID 36969561, 2023). "Regular exercise stimulated the expression of BDNF and TrkB in a stroke rat model, which can be negated by treatment with antisense BDNF oligonucleotide." (PMID 35821455, 2023). "As an essential modulator of synaptic plasticity in the central nervous system, BDNF supports neuronal survival and promotes the growth and differentiation of new neurons, which exerts positive implications for stroke recovery." (PMID 37153779, 2023). "MAPK signalling is needed for inducing synaptic plasticity alongside brain-derived neurotrophic factor (BDNF), which also plays an important role in neural plasticity and brain recovery following stroke." (PMID 35639336, 2023). "A decrease in serum BDNF levels was confirmed in stroke patients in two systematic reviews that included 26 RCTs and 62 case–control studies, respectively." (PMID 38137853, 2023). "Future studies focusing on ethnicity should be conducted to investigate the role that BDNF genotype actually plays in stroke occurrence." (PMID 38137853, 2023). "NSCs transfected with Lenti-BDNF were transplanted around the site of the infarct on Day 7 after the stroke." (PMID 37365654, 2023). "Low levels are related to poor prognosis whereas increased BDNF can be induced by physical exercise, thus enhancing the prognosis even in chronic post-stroke subjects." (PMID 37175644, 2023). "This represents an exciting opportunity to utilise an animal model’s divergence from human physiology to explore the potential of biomarkers like brain-derived neurotrophic factor (BDNF) to harness restoration following TBI or stroke." (PMID 38137157, 2023). "Our findings are, nevertheless, in line with a recent meta-analysis summarizing seven publications where BDNF serum levels in stroke patients during the acute phase were compared to control groups." (PMID 35756121, 2022). "Except for post-stroke, it has been reported that BDNF level was significantly decreased at the acute phase of CIS and it can act as a factor warning poor prognosis for the functional status of patients on the 90th day after onset." (PMID 36158555, 2022).
Stroke (continued). "For example, Ke and colleagues employed an animal model of stroke to measure the ability of aerobic exercise to recover motor behavior function and increase brain-derived neurotrophic factor (BDNF) protein levels in the hippocampus." (PMID 36233029, 2022). "The levels of BDNF were lower in the stroke patients than in the healthy controls, irrespectively of age." (PMID 35756121, 2022). "Methodological characteristics and main results of studies assessing the effects of endurance exercise on the BDNF concentration post-stroke." (PMID 35743624, 2022). "We confirm that exercises and rehabilitation programs promote BDNF production and motor recovery following stroke." (PMID 35287688, 2022). "Over the recent decades, circulating MMP-9 and BDNF concentrations have been found to have potential value in stroke diagnosis and prognosis." (PMID 36092813, 2022). "We detected a substantial decrease in plasma BDNF in the stroke patients compared to the healthy controls." (PMID 35756121, 2022). "It has been shown that endogenous BDNF and its receptor, tyrosine kinase (Trk) B, are increased under conditions of pathological change after stroke." (PMID 35177977, 2022). "EA pretreatment can increase the expression of GAP-43 and BDNF and alleviate ischemic injury and promote axonal regeneration, thereby providing protection for functional recovery following stroke." (PMID 36440366, 2022). "Literature shows the impacts of training on post-stroke circulating BDNF levels vary based on the program’s duration and intensity." (PMID 35287688, 2022). "It is documented that BDNF expression increased following different types of stroke such as intracerebral hemorrhage and ischemic stroke." (PMID 35879657, 2022). "In another study, the levels of BDNF in stroke patients measured within 10 days after stroke onset (median: 4 days) were found to be reduced compared to the controls." (PMID 35756121, 2022). "Only one fair-quality study has evaluated the effect of multiple sessions of aerobic exercise plus physical therapy care in post-stroke individuals and reported increased serum BDNF levels." (PMID 36556107, 2022). "Taken together, publications report lower BDNF levels in plasma or serum from stroke patients compared to controls during the early phase of a stroke." (PMID 35756121, 2022). "Low-frequency rTMS can promote the secretion of BDNF by the central nervous system of stroke patients." (PMID 35711903, 2022). "Cook utilized BDNF-loaded hyaluronic-acid hydrogels to locally release BDNF in the infarct cavity of a mouse stroke model for neural repair in the chronic phase after stroke." (PMID 35458307, 2022). "The present study is, however, in line with the majority of studies showing reduced BDNF levels in stroke patients compared to healthy controls." (PMID 35756121, 2022). "Subjects with stroke, n = 1856, showed lower BDNF levels compared to HC, n = 1191 (SMD [95%CI] = − 1.04 [− 1.49 to − 0.58])." (PMID 35287688, 2022). "Studies using animal stroke models have shown that multiple sessions of aerobic exercise can increase central BDNF concentrations, while BDNF responses following functional exercises, such as reaching and CIMT, are inconsistent." (PMID 36556107, 2022). "It was shown that BDNF levels during the first day after stroke are notably higher among patients under 65 years compared to older patients." (PMID 35055089, 2022). "An activity-driven increase in peri-infarct BDNF has been shown to promote motor recovery after stroke." (PMID 36556107, 2022). "For example, rs6265 (val66met) on brain-derived neurotrophic factor (BDNF) significantly affected neuroplasticity after stroke in Chinese, Iranian, Korean and East Asian populations." (PMID 35959401, 2022). "BDNF expression was also found to be significantly lower in the prefrontal cortex and hippocampus of the stroke + stress and stress only rats, which increased with BDNF administration." (PMID 36429060, 2022).